ALK (ALK receptor tyrosine kinase)
Diseases named in the same sentence as ALK in open-access papers (continued):
Sharing a sentence is not in itself a finding about the gene and the disease.
lung cancer (continued). "This study illustrated that STAT3 mediates treatment-induced adaptive survival of ALK-rearranged lung cancer cells through transcriptional regulation of apoptosis, identifying STAT3 as a promising therapeutic target of the combination therapy aimed at tumor eradication." (PMID 35228642, 2022). "However, a recent study on lung carcinomas showed that immunohistochemistry is superior to FISH in the detection of altered ALK." (PMID 35204520, 2022). "The distribution of TMB had not been fully characterized in Chinese lung cancer patients with no EGFR or ALK mutations." (PMID 33643802, 2021). "The use of 3D imaging for the detection of ALK fusion in CTCs was tested in a small cohort of lung cancer patients: comparing subjects with ALK-positive and ALK-negative NSCLC, the assay was able to capture a good probes signal separation, indicative of ALK translocations, by nuclear volume imaging." (PMID 34680298, 2021). "Besides, patients with ALK-positive lung cancers were significantly younger and were found at higher clinical stage at diagnosis compared with EGFR mutant cohorts." (PMID 34234236, 2021). "In general, EGFR was an important factor in the beginning of lung cancer and then play a decreased role in developed lung cancer and ALK fusions may occur at a later stage in the progression of lung cancer." (PMID 33976731, 2021). "Biopsy for ALK-positive lung cancer that progressed after chemotherapy for SCLC transformation might be useful for decision-making regarding the therapeutic strategy." (PMID 34401280, 2021). "The uterus is an uncommon site for metastasis from lung cancer, and our case indicated that serial gene analysis could provide new information about ALK inhibitor resistance." (PMID 34184417, 2021). "Anaplastic lymphoma kinase (ALK) is a transmembrane tyrosine kinase receptor that is frequently rearranged, mutated or amplified in specific neoplastic diseases, including lymphoma, neuroblastoma, lung cancer and, albeit to a lesser extent, melanoma." (PMID 34199079, 2021). "Typically, other driver mutations (e.g., EGFR, ALK, and ROS) of lung cancer tend to occur in never-smokers." (PMID 34205733, 2021). "Interestingly, these fusion mutation mechanisms of resistance, both on target and off-target, were described analogously in other cancer types such as ALK fusion-positive lung cancer and ROS1 fusion-positive lung cancer." (PMID 34829820, 2021). "Moreover, many studies have described the genetic susceptibility to develop lung cancer especially in North Africa by identifying genetic biomarkers in EGFR, KRAS and ALK genes." (PMID 33937056, 2021). "Developing inhibitors targeting these genomic aberrations may allow us to emulate current lung cancer model, in which the 5% to 6% of patients with non–small cell lung cancer who have an ALK rearrangement are treated with an ALK inhibitor." (PMID 33921181, 2021). "Patients of ALK rearrangement lung cancer shows drug resistance to lorlatinib; these mechanisms include epitheilial-mesogenic transition susceptible to combined ALK/Src inhibition, ALK compound mutations, and a novel bypass mechanism, mediated by Nf2 loss and outcome by mtor inhibition." (PMID 34976824, 2021). "Based on TMB and ITH, survival analyses were performed to identify their predictive and prognostic value for first-line chemotherapy in lung cancer patients without EGFR/ALK mutations." (PMID 34604048, 2021). "These targetable RTK rearrangements consist of ALK fusion in lung cancer and anaplastic large cell lymphoma, ROS1 fusion in lung cancer and glioblastoma, RET fusion in lung and thyroid cancer, FGFR fusion in bile duct and urothelial carcinoma, as well as NTRK fusion in pan-cancer." (PMID 34650924, 2021). "In lung cancer and lymphoma, ALK fusion is the most common aberration." (PMID 34591871, 2021). "Hence, is it possible to screen systematically for ALK fusions with tissue biopsies not only from lung adenocarcinomas, but also from other lung cancer subtypes?" (PMID 33467720, 2021).
lung cancer (continued). "ALK and EGFR mutations coincide at a relatively low frequency in lung cancer patients." (PMID 34654390, 2021). "In the current study, we analyzed the clinical characteristics and prognosis of 80 ALK rearranged lung cancer patients who underwent radical surgical treatment in our department between 2016 and 2019 with 3031 ALK‐negative lung adenocarcinoma patients as controls." (PMID 34596344, 2021). "ALK rearrangements were shown to be associated with increased VTE risks in patients diagnosed with non-small lung cancer, while there was no significant relation observed between VTE risks and EGFR or KRAS mutations in lung cancer patients." (PMID 33996610, 2021). "For the first time, we revealed that SPP1 overexpression is associated with poor outcomes in ALK fusion lung cancer patients who did not receive targeted therapy." (PMID 34234236, 2021). "Furthermore, the total of 521 patients with lung cancer were screened for ALK fusion through immunohistochemistry of ALK (ALK IHC), and ALK FISH analysis was performed in ALK IHC positive cases." (PMID 34234236, 2021). "Therefore, we found a significant upregulation of SPP1 expression in ALK-positive lung cancers compared to ALK-negative lung cancers and paired adjacent normal tissues (P < 0.0001)." (PMID 34234236, 2021). "Approximately 5–7% of non–small cell lung cancer (NSCLC) cases harbor an anaplastic lymphoma kinase (ALK) fusion gene and may benefit from ALK inhibitor therapy." (PMID 34559836, 2021). "Furthermore, we estimated clinical outcome for ALK-positive patients with lung cancer treated with ALK inhibitor or platinum-based chemotherapy." (PMID 34234236, 2021). "Interestingly, ALK rearrangements occur mainly in adenocarcinoma, but though rare can be detected in other histological subtypes of lung cancers such as squamous cell carcinoma and rarely in pulmonary lymphoepithelioma-like carcinoma." (PMID 33467720, 2021). "Improved understanding of the biology of lung cancer has resulted in the development of new biomarker-directed therapies targeting molecular alterations (eg, EGFR mutations, ALK rearrangements, ROS1 rearrangements, and BRAF V600E mutations), which have prolonged survival of lung cancer patients." (PMID 33442422, 2021). "These authors point out that the mechanisms of resistance to NRG1-targeting agents could be potentially explained by the upregulation of NRG1 as well as parallel pathway activation, as seen in HER2-positive breast cancer models and ALK-positive lung cancer." (PMID 34680187, 2021). "This strategy is developed whatever the detection of an ALK mutation in the tumor, since ALK-positive lung cancers are sensitive to these inhibitors, even in the absence of an ALK mutation." (PMID 33467720, 2021). "Combined TAE684 (ALK tyrosine kinase inhibitors) with PI3K inhibitor synergistically inhibited the proliferation of EML4-ALK-positive lung cancer cells and inhibition of PI3K/AKT signaling may conquer resistance to ALK-targeted treatment." (PMID 34234236, 2021). "After lung cancer subtyping is complete, non LUSC are evaluated for targetable driver genomic alterations such as epidermal growth factor receptor (EGFR) mutations, anaplastic lymphoma kinase (ALK) rearrangements, c-Ros oncogene 1 (ROS1) rearrangements, and BRAF V600E mutation." (PMID 33937015, 2021). "The history of research and development of EGFR-TKI and ALK inhibitors in lung cancer treatment reveals that finding clear driver genes for tumors is of great significance for developing new drugs, selecting the right treatment population and ensuring the therapeutic efficacy of targeted drugs." (PMID 34168983, 2021). "Hence, different clinical trials evaluated the potential clinical benefits of immune check-point inhibitors (ICIs) in ALK positive lung cancer patients." (PMID 33467720, 2021).
lung cancer (continued). "The discovery of the fusion gene nucleophosmin (NPM)-ALK, a result of a t (2:5) translocation, in anaplastic large-cell lymphoma (ALCL) has led to the identification of targetable ALK fusion genes in ALCL and other malignancies, such as EML4-ALK in lung cancer." (PMID 34072040, 2021). "Due to this, there remains a reliance on chemotherapy; in contrast, in paradigms like epidermal growth factor receptor (EGFR)-mutant lung cancer and anaplastic lymphoma kinase (ALK)-translocated lung cancer, effective targeted therapy has mitigated the need of chemotherapy." (PMID 33589591, 2021). "We hypothesized that ALK-positive lung cancer cells augment the activity of bone resorption via promoting the differentiation of osteoclasts by secreting SPP1 and lead to osteolytic bone metastasis." (PMID 34234236, 2021). "Thus, ALK inhibitors have demonstrated superior efficacy to platinum-based chemotherapy as front-line treatment for patients with ALK-positive lung cancer." (PMID 34234236, 2021). "Accordingly, we investigate the evolutionary histories of anaplastic lymphoma kinase (ALK)—which can underlie tumorigenesis in neuroblastoma, nonsmall cell lung cancer, and anaplastic large-cell lymphoma—its close relative leukocyte tyrosine kinase (LTK) and their candidate ligands." (PMID 33196781, 2021). "Lung cancers show a predilection to metastasize to bone, and the number of osteoclasts is increased at metastatic sites, which is accordance with osteoclast differentiation of ALK-positive lung cancer cells in our findings." (PMID 34234236, 2021). "However, the role of TTF1 in lung cancer pathogenesis and its relationship with the ALK translocation status is unclear." (PMID 32876329, 2021). "We identified the clinicopathological features and DDR mutation spectrum of 122 advanced lung cancer samples without EGFR or ALK mutations/translocations." (PMID 34604048, 2021). "Our study is the first to study the lung cancer patients’ mutation spectrum in the Chinese population without EGFR or ALK driver gene mutations." (PMID 33643802, 2021). "EGFR and ALK alternations often contribute to human malignancies, including lung cancer." (PMID 34654390, 2021). "Moreover, a clear association exists between the initial degree of tumor shrinkage and progression free and overall survival in ALK + lung cancer patients treated with TKIs and colorectal cancer patients treated with cetuximab." (PMID 33485341, 2021). "In our study, we found that worse PFS was frequent in specific DDR-altered lung cancer patients without EGFR or ALK mutations." (PMID 34604048, 2021). "There might be multiple reasons for the different effects of ALK fusion on the prognosis of lung cancer." (PMID 34596344, 2021). "Interestingly, we found increased mRNA of ROS1 and MET in ALK-positive lung cancer, the molecular mechanism is unclear at present." (PMID 34234236, 2021). "Ongoing clinical trials assessing the efficacy of ALK inhibitors in lung cancer." (PMID 34722241, 2021). "Furthermore, we found increased mRNA of PIK3CB, PIK3CD, PIK3CG, BCL2, TUBB3 in ALK-positive lung cancer, which suggested activation of PI3K/AKT signaling pathway." (PMID 34234236, 2021). "ALK and p-ALK status were investigated in the nine established MCC cell lines and in the lung carcinoma cell line NCI-H2228, which harbors a fusion gene formed from genes Echinoderm microtubule-associated protein-like 4 (EML4) and ALK, and was used as a positive control." (PMID 34029351, 2021). "While the development of immunotherapy against lung cancer with driver mutations and neuroendocrine tumors is ongoing, little is known about the TIME of large cell neuroendocrine carcinoma (LCNEC) or anaplastic lymphoma kinase (ALK) rearrangement-positive lung cancer." (PMID 33352665, 2020).
lung cancer (continued). "This phenomenon has an important practical implication, i.e., that tumor specimens collected from different anatomic sites or even the same anatomic site but at different time points in a lung cancer patient may need to be tested for ALK status." (PMID 32674491, 2020). "YAP1 was activated when ALK-rearranged lung cancer cells were exposed to ALC." (PMID 31900393, 2020). "Despite the promising clinical efficacy of the second-generation anaplastic lymphoma kinase (ALK) inhibitor alectinib in patients with ALK-rearranged lung cancer, some tumor cells survive and eventually relapse, which may be an obstacle to achieving a cure." (PMID 31900393, 2020). "The influence of common lung cancer mutations (i.e., EGFR, ALK, etc.)or programmed cell death-ligand 1 (PD-L1) in the PFDN expression could be elucidated in this further study." (PMID 32344577, 2020). "A treatment targeting YAP1 and ALK has potential as an effective therapy for YAP1-dependent ALC-resistant ALK-rearranged lung cancer, and may reduce the regrowth of ALK-positive lung cancer." (PMID 31900393, 2020). "More than one lung cancer specimen from the same patient over time may be collected for ALK testing." (PMID 32674491, 2020). "Therefore, ALK inhibitors in lung cancer can be openly considered for use in Indonesian patients to improve the outcome of this subset of patients." (PMID 33425389, 2020). "ALK inhibitors are used in targeted therapy of ALK-positive cancers, especially lung cancer." (PMID 32344689, 2020). "Hence, crizotinib was approved in November 2013 in the second-line setting for ALK-rearranged lung cancer patients after disease progression on platinum doublet therapy." (PMID 33352844, 2020). "The diagnosis of ALK-translocated lung cancer took place in 3–5% in all NSCLC patients." (PMID 32164629, 2020). "As personalized medicine is currently gaining popularity, our findings for crizotinib may contribute to effective prescriptions to prevent further development of drug-resistant cancer in lung cancer patients who have c-MET and ALK mutation phenotypes." (PMID 32528877, 2020). "Therefore, we retrospectively assessed the efficacy and tolerability of lorlatinib in patients with ALK-positive or ROS1-positive lung cancer." (PMID 33171712, 2020). "The PATH panel was designed to cover most targetable mutations and amplifications for lung cancer, colorectal cancer, melanoma, and GIST for first line treatment options, as well in the setting of therapy resistance (e.g. EGFR, ALK and KIT gatekeeper mutations)." (PMID 32264863, 2020). "ALC exhibited significant anti-tumor activity against ALK-rearranged lung cancer; however, achieving complete tumor eradication was generally difficult at the early stage of treatment, suggesting that some tumor cells survived the ALC treatment (initial survival)." (PMID 31900393, 2020). "Immunotherapy targeting programmed cell death receptor 1/ligand 1 (PD‐1/PD‐L1) has been shown to exhibit good effect and durable response in epidermal growth factor receptor (EGFR) and anaplastic lymphoma kinase (ALK) wild‐type non‐small cell lung cancer (NSCLC) patients." (PMID 32500560, 2020). "Similarly, in another series of 42 ALK-mutant lung cancer treated with crizotinib, the higher 8-weeks volume reduction was significantly associated with longer survival." (PMID 32321474, 2020). "Since ALK-rearranged lung cancer may occur in youth, the development of curative treatment is an urgent issue." (PMID 31900393, 2020).
lung cancer (continued). "ALK, a receptor tyrosine kinase, was originally identified in lung cancer in 2007 with the detection of an echinoderm microtubule-associated protein-like 4 (EML4) gene and anaplastic lymphoma kinase (ALK) gene fusion from a surgically resected lung adenocarcinoma patient." (PMID 32549358, 2020). "Acquired drug resistance to ALK inhibitors prevents the effective management of lung cancer." (PMID 32558295, 2020). "Patient 1 is a 59-year-old lady with metastatic ALK-rearranged lung cancer." (PMID 32963526, 2020). "Combinatorial therapy against ALK and YAP1 in the early stages of treatment may reduce the recurrence of ALK-positive lung cancer." (PMID 31900393, 2020). "In its recent evaluation of alectinib, the French health authority stated that, in light of the superior efficacy and safety of alectinib compared to crizotinib demonstrated in the ALEX trial, alectinib should be the treatment of choice in the first line treatment of ALK+ lung cancer." (PMID 31945065, 2020). "Summing up this interesting data, synergistic effects of combined TAE684 and radiotherapy in EML4‐ALK positive lung cancer cells are demonstrated: Not only does ALK‐inhibition enhance the effect of canonical photon radiotherapy, but also of particle irradiation using carbon ions." (PMID 31799812, 2020). "Subsequently, ALK translocations were also found in other cancers, such as lung cancers." (PMID 31924270, 2020). "Lung cancer is well established as a highly heterogeneous tumor that harbors various gene alterations including mutations in EGFR, KRAS, BRAF, PD-L1, and PIK3CA, as well as ALK rearrangement and HER2 amplification." (PMID 33411683, 2020). "For example, in advanced lung cancer, driver gene mutations like EGFR and ALK have been shown to be associated with reduced response rates to ICIs and low TMB; therefore, the FDA does not recommend first-line ICI treatment in patients with EGRF or ALK-positive tumors." (PMID 33163406, 2020). "Given the low occurrence rate of ALK in lung cancer, multicenter participation and predefined subgroup analysis of these rare ALK variants may be worth considering in future studies." (PMID 32974126, 2020). "If the results of this study are better than the current standard of care, genomic testing upon progression, and individualized medicine could become the standard of care for ALK lung cancer progression." (PMID 32397295, 2020). "Therefore, unambiguous identification of ALK status in a lung cancer specimen plays a vital role in the clinical management of these patients." (PMID 32674491, 2020). "However, patients with ALK-positive lung cancer were more likely to express PDL1 in TC than patients without ALK rearrangements." (PMID 32127616, 2020). "Monotherapy using YAP1 inhibitors may therefore have potential to suppress tumor growth in some ALK-rearranged lung cancers." (PMID 31900393, 2020). "Currently, lung cancers are screened for actionable mutations, to identify cases suitable for targeted therapies, including those targeting mutations in EGFR, BRAF and rearrangements in ALK or ROS1." (PMID 32898185, 2020). "STRN, a calmodulin-binding protein member, is a partner of ALK protein, and its fusion protein, which was identified in thyroid and lung carcinoma, leads to constitutive activation of ALK tyrosine kinase via dimerization mediated by the coiled-coil domain of STRN." (PMID 31936239, 2020). "Moreover, previous studies in NPM-ALK+ T cell lymphoma as well as ALK+ lung cancer have shown cross-resistance among various ALK inhibitors." (PMID 31340850, 2019). "Patients with lung cancer that carry EML4-ALK fusion respond to tyrosine kinase inhibitors (TKI), such as crizotinib, and therefore unambiguous detection of ALK status in a lung cancer specimen is critical for a treatment decision and predicts the outcome of the affected patient." (PMID 31412611, 2019). "This will shed light on drug resistance mechanisms in ALK-translocated lung cancer." (PMID 30658414, 2019).